UBOX5 (U-box domain containing 5)
Description:
May have a ubiquitin-protein ligase activity acting as an E3 ubiquitin-protein ligase or as a ubiquitin-ubiquitin ligase promoting elongation of ubiquitin chains on substrates.
Synonyms: hUIP5; KIAA0860; RNF37; UBCE7IP5; UIP5
Tractability: PROTAC: ubiquitination databases record sites on it.
Gene: Protein-coding gene on chromosome 20 (3,107,573 to 3,160,196, reverse strand). Ensembl gene ENSG00000185019.
Subcellular location: Nucleus
Subcellular location (Human Protein Atlas): Nucleoplasm
Pathways (Reactome):
Immune System: Antigen processing: Ubiquitination & Proteasome degradation
Gene Ontology:
Molecular function: protein binding; ubiquitin protein ligase binding; ubiquitin protein ligase activity; ubiquitin-ubiquitin ligase activity; ubiquitin-protein transferase activity
Biological process: protein polyubiquitination; protein ubiquitination
Cellular component: nuclear body; nucleus
Genetic constraint (gnomAD): Loss-of-function variants: 28 observed, 40.78 expected, observed/expected ratio (o/e) 0.69, 90% interval 0.51 to 0.94. The upper end of that interval is the gene's LOEUF score, 0.94, which puts it in group 3 of 6, group 1 being the genes least tolerant of losing a copy. Missense variants: 585 observed, 709.94 expected, observed/expected ratio (o/e) 0.82, 90% interval 0.77 to 0.88. Synonymous variants: 283 observed, 291.17 expected, observed/expected ratio (o/e) 0.97, 90% interval 0.88 to 1.07.
Homologues: Orthologues: chimpanzee UBOX5 (99% identical), macaque UBOX5 (98% identical), rabbit UBOX5 (88% identical), pig UBOX5 (87% identical), guinea pig UBOX5 (82% identical), mouse Ubox5 (79% identical), rat Ubox5 (79% identical), tropical clawed frog ubox5 (56% identical), zebrafish ubox5 (33% identical), Drosophila melanogaster CG2218 (22% identical).
Diseases named in the same sentence as UBOX5 in open-access papers:
UBOX5 is named in the same sentence as 3 diseases in open-access papers, as found by Europe PMC text mining. Sharing a sentence is not in itself a finding about the gene and the disease. The quoted sentences say what the papers report.
primary angle-closure glaucoma (1 paper, 2025). An angle-closure glaucoma characterized by closure of the anterior chamber angle by an intrinsic defect such that aqueous outflow is blocked and the intraocular pressure becomes inappropriately elevated leading to optic nerve damage and visual field loss. "Our findings suggest the UBOX5—BIP signalling pathway might be involved in biology of primary angle-closure glaucoma." (PMID 40817263, 2025).
UBOX5 also shares sentences with these, for which no sentence is quoted: cardiac hypertrophy (1 paper); tumor (1).